EPHA7 (EPH receptor A7)
Diseases named in the same sentence as EPHA7 in open-access papers (continued):
Sharing a sentence is not in itself a finding about the gene and the disease.
meningioma (1 paper, 2023). A generally slow growing tumor attached to the dura mater. "Many signature genes in this subpopulation, including SULT1E1, EDNRA, and EPHA7, were highly expressed in grade II/III meningioma samples." (PMID 36994665, 2023).
mesothelioma (1 paper, 2022). A usually malignant and aggressive neoplasm of the mesothelium which is often associated with exposure to asbestos. "By contrast, the phospho-RTK array data suggested that EGFR, RYK and EphA7 are activated upon progranulin stimulation of mesothelioma cells." (PMID 36471440, 2022). "Our data suggest that EphA7 might have a tumor suppressive role in mesothelioma, since EphA7 depletion did not prevent progranulin-dependent AKT and MAPK activation but led instead to an increase in basal activation of these two signaling pathways." (PMID 36471440, 2022).
nevus (1 paper, 2022). Nevus (or naevus, plural nevi or naevi, from nævus, Latin for "birthmark") is the medical term for sharply circumscribed[1] and chronic lesions of the skin or mucosa. "The expression level of EphA7 receptor in BCC, benign skin diseases, and compound nevus was checked using a specific anti-EphA7 polyclonal antibody for immunohistochemistry." (PMID 35103233, 2022). "In this study, we examined the EphA7 expression in a set of BCCs, benign skin diseases, and compound nevus tissue samples." (PMID 35103233, 2022). "We checked EphA7 expression levels and methylation status in a set of BCCs, benign skin diseases, and compound nevus tissue samples using immunohistochemistry." (PMID 35103233, 2022).
Oesophageal cancer (1 paper, 2020).
ovarian serous adenocarcinoma (1 paper, 2017). An adenocarcinoma that arises from the ovary and is characterized by the presence of malignant epithelial cells that, in well differentiated tumors, resemble the epithelium of the fallopian tube or, in poorly differentiated tumors, show anaplastic features and marked nuclear atypia. "EPHA7 protein was detected in both ovarian serous adenocarcinoma and endometrioid adenocarcinoma cancer cells." (PMID 28611294, 2017).
pancreatic adenocarcinoma (1 paper, 2020). "In pancreatic adenocarcinomas, patients with moderate or high EphA5 and EphA7 expression had shorter survival times compared to the low-expression group." (PMID 33007931, 2020).
pyometra (1 paper, 2015). "Conversely, the EPHA7 (ephrin receptor A7) gene was detected as having the lowest fold change in pyometra." (PMID 26222498, 2015).
retinal diseases (1 paper, 2021). "EphrinA1, ephrinA4, ephrinA5, EphA2, EphA7, ephrinB2, EphB3, and EphB4 seem to be the most important in the context of retinal diseases." (PMID 34201393, 2021).
triple-negative breast carcinoma (1 paper, 2022). An invasive breast carcinoma which is negative for expression of estrogen receptor (ER), progesterone receptor (PR), and human epidermal growth factor receptor 2 (HER2). "The current study aims to investigate the clinical significance of EPHA2, EPHA4, and EPHA7 expression in triple-negative breast cancer (TNBC) cases." (PMID 35204461, 2022).
uveal melanoma (1 paper, 2020). A melanoma derived from melanocytes of the uveal tract. "The aim of the study was to evaluate the expression of ephrin receptors EphA1, EphA5, and EphA7 in uveal melanoma and its associations with clinicopathological parameters, overall survival, and disease-free survival." (PMID 33007931, 2020). "The present study aimed to assess EphA1, EphA5, and EphA7 expression in uveal melanoma, combined with clinicopathological parameters, overall survival, and disease-free survival." (PMID 33007931, 2020).
tumor (58 papers, 2008 to 2025). "In ND2-SmoA1 transgenic mice, loss of ephrin-A5—along with EphA4 and EphA7—significantly reduced tumor size and p-Akt levels." (PMID 41200151, 2025). "EphA5 and EphA7 are associated with tumor growth, with higher expression correlating with shorter survival." (PMID 39839790, 2024). "To further investigate the association between anti-tumor immunity and EPHA7-MUT across multiple cancer types, we thoroughly examined immune-related genes within each cancer type." (PMID 33526018, 2021). "Research in this field has recently identified EPHA7, a tumor suppressor gene found on 6q that encodes the protein Ephrin type-A receptor 7, a receptor tyrosine kinase that mediates developmental events in the nervous system." (PMID 34944845, 2021). "High expression of EphA7 was associated with a more frequent primary tumor location in the posterior pole." (PMID 33007931, 2020). "The downregulation of receptor tyrosine kinase EphA7 is frequent in epithelial cancers and linked to tumor progression." (PMID 29022918, 2017). "Elevated EphA7 expression was significantly associated with older patients’ age, presence of fibrosis and smaller tumor size (p = 0.036, p = 0.029 and p = 0.018, respectively)." (PMID 24495444, 2014). "For example, relapse samples gained mutations in transmembrance receptor tyrosine kinase genes EPHB2 and EPHB6, whose family member EPHA7 encodes a known soluble tumor suppressor for FL." (PMID 25123191, 2014). "EphA7 expression was significantly associated with patients’ age (p = 0.026) and borderline with tumor size (p = 0.085)." (PMID 24495444, 2014). "EPHA7 expression was positively associated with tumor MVD, increased age, and decreased OS." (PMID 34445116, 2021). "The level of EphA7 hypermethylation was positively correlated with the tumor purity of CESCs (cor = 0.115, P < 0.05)." (PMID 40258813, 2025). "In this study, we first demonstrated that EphA7 functions as a tumor suppressor in CC via the PI3K/AKT signaling pathway by activating endogenous EphA7 expression via demethylation." (PMID 40258813, 2025). "The epigenetic reactivation of EphA7 via dCas9-TET1 reduced tumor growth and enhanced sensitivity to chemo-, radio- and immunotherapy by modulating SP1/DNMT1 and PI3K/AKT signalling." (PMID 41403730, 2025). "This largely agrees with what has been recently postulated in the literature except for EPHA7, which is most often referred to as a tumour suppressor, though it also has roles in promoting tumours." (PMID 41152984, 2025). "EPHA7 is a member of the protein‐tyrosine kinase family and plays a dual part of an oncogene or tumor suppressor in intercellular signal transduction and the regulation of cell proliferation and differentiation as well as resistance to chemotherapy drugs." (PMID 37937323, 2023). "There were a total of 21 HumanMethylation 450 probes located in the EphA7 gene and 11 probes in the promoter region that exhibited significant differences (P < 0.05) between tumor tissues and adjacent normal specimens." (PMID 35681118, 2022). "Particularly, EPHA7 has been previously identified as a tumor suppressive gene that inhibits tumor growth and progression in various cancers." (PMID 33526018, 2021). "Clinical trials with expression data are needed to expand our findings and test the added value of tumor-infiltrating lymphocytes in the survival analysis of EPHA7-MUT." (PMID 33526018, 2021). "These tumour-suppressive abilities involve the enhancement of tumour cell apoptosis, which is dependent on ligand stimulation as EphA7 mutants that cannot be phosphorylated were unable to exert these same effects." (PMID 33430066, 2021). "And we uncovered that mutated EPHA7 was predictive of better clinical outcomes in patients receiving ICI therapy and strongly associated with enhanced anti-tumor immunity across multiple cancer types." (PMID 33526018, 2021).
tumor (continued). "We found EPHA7-MUT was significantly associated with better clinical outcomes in ICI-treated patients and enhanced anti-tumor immunity." (PMID 33526018, 2021). "Overexpression of wild-type (WT) EphA7 in PCa cells resulted in decreased tumor volume and increased tumor apoptosis in primary tumors." (PMID 29022918, 2017). "Previous studies indicated that Epha7 negatively regulates cell proliferation and trigger for apoptosis in a caspase-3-dependent manner and Fhit is tumor-suppressor gene in relation to induction of apoptosis and cell cycle alteration." (PMID 29255466, 2017). "In sum, receptor phosphorylation of EphA7, at least in part, suppress PCa tumor malignancy through targeting PI3K/Akt signaling pathways." (PMID 29022918, 2017). "In the present study, we provide substantial evidence that EphA7, as a tumor suppressor, restrains PCa cell migration and invasion via delaying cell growth and inducing cell apoptosis in response to its cognate ligand ephrinA5." (PMID 29022918, 2017). "In conclusion, the phosphorylated EphA7 can exert potential tumor-suppressive effects in regulating the development and progression of PCa." (PMID 29022918, 2017). "EPHA7 is inactivated by DNA hypermethylation in several tumor types, and our data suggest that elevated BMI1 levels contribute to this alteration." (PMID 27533460, 2016). "The reduction of EPHA7 gene expression in these tumor types can be explained by increased genomic methylation and genomic deletion of this locus with the former being a frequent event." (PMID 27533460, 2016). "Western blot analysis of tumor tissue harvested from EphA4−/−EphA7−/−Smo, EphA4+/−EphA7−/−Smo, and EphA4+/+EphA7−/−Smo mice revealed expression of p-Akt and PCNA that correlated with actual tumor size." (PMID 26345456, 2015). "EphA7 expression showed trends of correlation with the presence of fibrosis (p = 0.070) and tumor size (p = 0.081)." (PMID 24495444, 2014). "Elevated EphA4 expression was also significantly associated with low stage and presence of inflammation, while enhanced EphA7 expression with older patients’ age, presence of fibrosis and smaller tumor size." (PMID 24495444, 2014). "Moderate/high EphA7 expression was significantly more frequently observed in older patients, as well as in those with presence of fibrosis and smaller tumor size." (PMID 24495444, 2014). "In the present study, we investigated the immunohistochemical expression of EphA7 and correlated it with clinical pathological parameters and tumor vascularity." (PMID 18366728, 2008). "In 22 of 32 patients, EphA7 immunoreactivity was observed on the prominent membrane and cytoplasm of tumor cells showing different intensities of EphA7 protein." (PMID 18366728, 2008). "EphA7 represents a promising therapeutic target for tumor chemo-/immunotherapy in CC." (PMID 40258813, 2025). "In conclusion, our results comprehensively revealed that EphA7 may function as a tumor suppressor in CC by restraining tumor proliferation and invasion, promoting apoptosis, and modulating the PI3K/AKT signaling pathway in CC cells." (PMID 40258813, 2025). "Mutational profiling results indicated that the overall tumor mutation burden and the mutation frequency of the gene TTN were higher in the low expression group of AGTR1, SUSD5, and EPHA7, while the opposite trend was observed for DNER (Supporting Informmation)." (PMID 39556695, 2024). "In summary, most Eph receptors (EphA1, EphA2, EphA3, EphA4, EphA5, and EphA7) function as promoters of GC progression, influencing metastasis, tumor invasion, angiogenesis, and drug resistance, while EphA1 has a more complex role depending on tumor differentiation." (PMID 39839790, 2024). "The primary findings of these studies suggest that EphA7 may serve as an important tumor suppressor in CRC development, with genetic and epigenetic alterations regulating the tumor suppression." (PMID 38651144, 2024).
tumor (continued). "A previous IHC study on EphA7 protein expression in 352 cases of ESCC showed that the low expression of EphA7 was significantly associated with lymph node metastasis, low degree of tumor differentiation, and pTNM staging." (PMID 39839790, 2024). "In summary, while EphA2 promotes cancer progression in ESCC, EphA7, EphA3, and EphA5 act as tumor suppressors, suggesting that members of the Eph family may have opposing effects depending on the tumor context." (PMID 39839790, 2024). "EphA7 plays a role as a tumor suppressor in certain cancers." (PMID 35103233, 2022). "Additionally, EPHA5 overexpression was correlated with tumor proliferative capacity and longer OS and EPHA7 overexpression correlated with tumor proliferative capacity and older age, presence of fibrosis, as well as with smaller tumor size." (PMID 34445116, 2021). "Accumulation of fatty acids and glucose, and depletion of cholesterol and lactate within EPHA7-MUT tumor were detected in our analysis, which could create a better TIME and enable cytotoxic lymphocytes to work more effectively." (PMID 33526018, 2021). "Further gene set enrichment analysis revealed enhanced anti-tumor immunity in EPHA7-MUT tumor." (PMID 33526018, 2021). "Similarly, the average tumor weights of the PC-3/EphA7(WT) primary tumors were significantly less than those of the PC-3/Control tumors, the PC-3/EphA7(KD) tumors and the PC-3/EphA7(ΔCyto) tumors (P<0.05)." (PMID 29022918, 2017). "To evaluate whether the phosphorylation of the EphA7 receptor could affect tumor growth, we first analyzed the effect of different EphA7 mutants forms on tumor growth in vivo." (PMID 29022918, 2017). "Although our data suggest that a delayed DNA methylation process is initiated upon Bmi1 overexpression, investigation of different stages of tumor development in vivo will be required to better understand the dynamics and mechanisms of de novo DNA methylation at the EphA7 locus." (PMID 27533460, 2016). "Another important observation was EphA7 overexpression in both vasculature as well as tumor cells." (PMID 18366728, 2008). "Taken together, our data illustrated that EphA7 could be a potential candidate as a prognostic tumor marker and a new targeted therapeutic assessment in primary and recurrent GBM." (PMID 18366728, 2008). "Additional experimental work is necessary to unveil the biologic pathway linking Eph/ephrins with tumor growth in cancer cells and tumor-associated vessels of GBM and further studies are needed before EphA7 becomes established as an important prognostic and predictive tool in GBM." (PMID 18366728, 2008). "Whereas several studies in recent years have clearly indicated that altered expression of Eph receptors and ephrin ligands is associated with increased potential for tumor growth, angiogenesis, metastasis and adverse outcome, few studies have addressed the role of EphA7 in tumor pathogenicity." (PMID 18366728, 2008). "The unfavorable prognostic influence of EphA7 in GBM could be attributed to the well-recognised role of Eph RTKs in tumor angiogenesis." (PMID 18366728, 2008). "Based on our findings, there might be a possible relationship between EphA7 and tumor neovascularization." (PMID 18366728, 2008). "Interestingly, some of the common down-regulated genes, such as EPHA7 and NSUN7, are known for both their tumor suppressing and promoting roles, or are associated with overall survival (OS) (SLC22A31), while others have clear pro-tumorigenic roles (ADGRF1, LOX, LY6G5C, SNAI2, TNFRSF11B, ZNF233)." (PMID 36769365, 2023). "AEG-1 and EphA7 levels were lower in well-differentiated cases with small tumor size (<2 cm), no lymph node metastasis and no invasion compared to poorly-differentiated cases with large tumor size (>2 cm), lymph node metastasis and invasion into surrounding tissues and organs (p < 0.05)." (PMID 33671513, 2021).
tumor (continued). "However, their role in tumorigenesis remains controversial, as both tumor growth promoter and suppressor potential have been ascribed to Eph and ephrins while the function of EphA7 in GBM pathogenesis remains largely unknown." (PMID 18366728, 2008). "We performed in vivo knockdown experiments targeting AGTR1, DNER, EPHA7, and SUSD5 in BALB/c nude mice to investigate the effects of these recurrence mRNA panel genes on GC tumor growth and metastasis." (PMID 39556695, 2024). "However, other studies report the opposite showing that EPHA7 may act as a tumor suppressor." (PMID 33439936, 2021). "Finally, metabolic changes in EPHA7-MUT tumors could also strengthen anti-tumor immunity." (PMID 33526018, 2021). "Overall, EPHA7-MUT tumors are more likely to provide a friendly living environment for those effective immune cells and thus enhance the anti-tumor immunity." (PMID 33526018, 2021). "Four genes (EPHA7, SOCS2, SYNM, WNK2) are tumor suppressor genes whose hypermethylation is a common mechanism of downregulation." (PMID 28927421, 2017). "Statistical correlation was detected between the expression levels of EphA7 or MVD and clinical pathological parameters such as age, gender and tumor status." (PMID 18366728, 2008). "In double knockout mice lacking EphA4 and EphA7 (EphA4−/− EphA7−/− Smo), MRI and Western blot analyses showed no consistent changes in tumor size, despite correlations between tumor volume, p-Akt, and PCNA levels." (PMID 41200151, 2025). "Unlike the ephrin-A5 mice, data for the EphA4/EphA7 Smo mice did not yield any consistent patterns of variability in tumor size." (PMID 26345456, 2015). "Thus, ephrin-A5 could have been investigated as a potential tumor-suppressing ligand through the interaction with its tumor promoting receptors such as EPHA2, EPHA3, EPHA4, EPHA5, EPHA7, EPHA8, and EPHB2 in sarcomas." (PMID 35563562, 2022). "In 15 paired tissues, western blot analysis confirmed the overexpression of EPHA7 in tumor tissues compared with matched adjacent noncancerous tissues, and a correlation assay demonstrated the inverse correlation between EPHA7 protein expression and miR-944 expression, especially in AC tissues." (PMID 27681722, 2016). "However, knockout studies in mouse models lacking EphA4 and EphA7 revealed no significant impact on tumor size, suggesting that these receptors may not play a central role in tumor growth." (PMID 41200151, 2025).